UBE3A (ubiquitin protein ligase E3A)
Diseases named in the same sentence as UBE3A in open-access papers (continued):
Sharing a sentence is not in itself a finding about the gene and the disease.
neurodevelopmental disorder (continued). "In this review, we focus on one of the HECT E3 ligases, E6AP, which is also known as UBE3A and plays roles in oncogenesis, neurodevelopmental disorders, and other human diseases." (PMID 32751183, 2020). "Understanding the genome-wide influences of UBE3A will help uncover its role in early brain development and ultimately lead to identification of key therapeutic targets for UBE3A-related neurodevelopmental disorders." (PMID 30686997, 2018). "Here, we construct an orthogonal UB transfer (OUT) cascade to identify the substrates of E6AP, a HECT E3 also known as Ube3a that is implicated in cancer and neurodevelopmental disorders." (PMID 29263404, 2017). "Notably, Ube3a and Sirt1 are known to play a role in chromatin remodeling and neurodevelopmental disorders." (PMID 35466187, 2022). "In this review, we have discussed the roles of E6AP/UBE3A in the pathophysiology of cancers and neurodevelopmental disorders, and highlighted the E6AP-substrate interactions and downstream pathways that could be therapeutic targets." (PMID 32751183, 2020). "AS is a neurodevelopmental disorder caused by the lack of expression of the UBE3A protein, usually due to a deficiency of the maternal copy of the UBE3A gene." (PMID 32532103, 2020). "E6AP/UBE3A is widely known for its involvement in neurodevelopmental disorders." (PMID 32751183, 2020). "More recently, UBE3A genome-wide functions may enlighten additional gene pathways relevant to neurodevelopmental disorders." (PMID 30686997, 2018). "Their regulation by UBE3A provides molecular mechanisms to explain how synaptic integrity is maintained and how alteration of this interaction contributes in part to neuronal phenotypes in neurodevelopmental disorders." (PMID 27909399, 2016). "Additional structure-function analysis reveals that Q588 forms a regulatory site in UBE3A that is conserved among HECT domain ubiquitin ligases and perturbed in various neurodevelopmental disorders." (PMID 34815418, 2021). "We focused first on mouse models for AS, a neurodevelopmental disorder marked by the absence of the maternal Ube3a protein." (PMID 40070112, 2025). "The UBE3A gene resides within the human 15q11.2-q13.3 locus that is parentally imprinted in neurons leading to the non-Mendelian inheritance patterns of three human neurodevelopmental disorders." (PMID 30686997, 2018). "Interestingly, some of the proteins shown to be misregulated in AS and/or interact with UBE3A have also been shown to be disrupted in other neurodevelopmental disorders, including ASDs in which UBE3A is not reported to be misregulated." (PMID 26441497, 2015).
cancer (69 papers, 2007 to 2026). A tumor composed of atypical neoplastic, often pleomorphic cells that invade other tissues. "The genes BLK, FAM167A, STAT1, STAT4, TNPO3, and TNIP1 are associated with AIDs, and CDC37, DDX6, MAPT, STAT1, STAT4, and UBE3A are associated with cancers." (PMID 40429780, 2025). "The HECT (Homologous to the E6-AP Carboxyl Terminus)-family protein E6AP (E6-associated protein), encoded by the UBE3A gene, is a multifaceted ubiquitin ligase that controls diverse signaling pathways involved in cancer and neurological disorders." (PMID 32751183, 2020). "The cellular HECT domain E3 ubiquitin ligase E6AP (UBE3A) associates with papillomavirus E6 oncoproteins, which contribute to 5% of cancer deaths world-wide." (PMID 31971989, 2020). "Altogether we believe that our Drosophila E6+UBE3A model is an important new tool to study the molecular mechanism underlying HPV-mediated cancer and malignancy." (PMID 27537218, 2016). "Thus, developing enzymatic inhibitors of UBE3A is a viable option for treating HPV-associated cancers, given the general challenges associated with the development of potent and selective PPI inhibitors." (PMID 40002221, 2025). "E6AP, also known as UBE3A, is a HECT E3 ligase that has gained attention for its role in human papillomavirus (HPV)-associated cancers." (PMID 39851497, 2025). "Here in this study, we developed the first Drosophila model of HPV16-induced cancer through the expression of its main oncogenes, E5, E6, E7 in conjunction with human UBE3A." (PMID 36508448, 2022). "Ubiquitin-protein ligase E3A (UBE3A) reportedly promotes or suppresses various types of malignant tumors." (PMID 34421347, 2021). "Abnormal UBE3A activity is essential for the initiation and progression of several cancers." (PMID 40076922, 2025). "However, induced disruption of the Ube3a gene in postnatal mice does not cause any appreciable phenotype, suggesting that on-target adverse effects of UBE3A inhibitors would be minimal when used in adult cancer patients." (PMID 40002221, 2025). "E6AP, human papillomavirus (HPV) E6‐associated protein, also known as ubiquitin‐protein ligase E3A (UBE3A), is a multifaceted ubiquitin ligase that controls various signaling pathways involved in neurological diseases and cancers." (PMID 37454373, 2023). "It is interesting to mention that at least 20 of these individual institutes and centers are acknowledged as funders of AS research, with research emphasis ranging from child development to cancer, diabetes and kidney diseases, reflecting the different lines of research focusing on AS and UBE3A." (PMID 35637341, 2022). "The role of UBE3A in malignant tumors has been extensively studied." (PMID 35368029, 2022).
cancer (continued). "The molecular function of UBE3A in cancers depends, however, on specific tumor types." (PMID 33670160, 2021). "Our results are consistent with this view, as co-expression of E6+UBE3A was not sufficient to cause cellular transformation and cancer." (PMID 27537218, 2016). "However, the cancer-related role of UBE3A in RCC remains unclear, and more investigation should be performed in the future." (PMID 35368029, 2022). "Furthermore, UBE3A has a close association with non-virus related cancer." (PMID 34421347, 2021). "Quite a few E3s have been identified to mediate the proteasomal degradation of PML, including KLHL20, UHRF1, UBE3A and RNF4, which may drive the development of cancers at least partially through PML downregulation." (PMID 40002221, 2025). "The UBE3A gene does not have a direct link to cancer; however, it is involved in many pathways related to cancer biology, including protein degradation." (PMID 41200642, 2025). "Ube3a is important in neurodevelopment and cancer, but it is not well-studied in osteoclastogenesis." (PMID 35742859, 2022). "Studies of UBE3A in non-viral oncogenesis cancers have provided useful insights regarding its role in tumors." (PMID 34421347, 2021). "Thus, none of the other pathways tested showed any effect upon the E6+UBE3A phenotype, indicating that the effect of the insulin receptor is specific and suggesting that changes in insulin signaling may play a role in in the cell transformation and cancer progression induced by HPV." (PMID 27537218, 2016).
tumor (46 papers, 2004 to 2026). "The UBE3A gene encodes a key enzyme for the ubiquitin protein degradation system, apoptosis, tumor suppression, cell adhesion, and targeting proteins for degradation, autophagy, signaling pathways, and circadian rhythm." (PMID 41683698, 2026). "We showed that the inhibition of tumor growth caused by UBE3A knockdown could be attenuated by concurrent knockdown of ZNF185, both in vitro and in vivo." (PMID 34421347, 2021). "Among these genes, PKM, CAV1, GLI3, PICK1, PRPF6, and UBE3A have been identified as oncogenes, and play a pivotal role in orchestrating tumor-host interactions, fostering tumor growth, promoting metastasis, enhancing resistance to therapy, and ensuring cellular survival." (PMID 38280969, 2024). "Therefore, we presume that the function of UBE3A varies according to tumor type; its functions in specific tumors should be further explored." (PMID 34421347, 2021). "Importantly, UBE3A knockdown impeded tumor growth in vivo, while UBE3A rescue enhanced tumor growth in vivo." (PMID 34421347, 2021). "Inhibition of UBE3A combined with the senolytic agent ABT‐263 induced apoptosis and inhibited tumor growth." (PMID 41748542, 2026).
neurological diseases (25 papers, 2012 to 2025). "Altered expression of the E3 ubiquitin ligase UBE3A in the nervous system is associated with a variety of neurological disorders." (PMID 39197537, 2024). "E6AP is encoded by the Ube3A locus, which is mutated in a neurological disorder called Angelman Syndrome19." (PMID 31949242, 2020). "Angelman syndrome (AS) is a debilitating neurological disorder caused by mutation of the E3A ubiquitin protein ligase (UBE3A) gene." (PMID 33154971, 2020). "Misexpression of the E3 ubiquitin ligase gene UBE3A is thought to contribute to a range of neurological disorders." (PMID 39197537, 2024). "Recent studies have showed that UBE3A was involved in the etiology of many human tumors and neurological diseases." (PMID 33995501, 2021). "The regions of the 3 CNVs are located in chromosome Xp22.31, 15q11.2–13.1 and 17p11.2, and harbored genes associated with neurological diseases including GABRB3, UBE3A, MAGEL2, RAI1, ALDH3A2, ATPAF2 according to the database of Online Mendelian Inheritance in Man (OMIM)." (PMID 33753861, 2021). "Without proper levels of UBE3A by the HECT domain, an individual is likely to develop serious neurological disorders." (PMID 38248358, 2023).
infection (12 papers, 2016 to 2025). The state of being infected such as from the introduction of a foreign agent such as serum, vaccine, antigenic substance or organism. "In our system, infection of hippocampal neurons with a DD-Ube3A-expressing lentivirus resulted in undetectable expression of exogenous Ube3A in the absence of TMP." (PMID 30937395, 2019). "p18 expression was reduced by infection with a set of p18 shRNA lentiviruses, while Ube3a KD was achieved with Accell Ube3a siRNA." (PMID 30020076, 2018). "Impacts of UBE3A on the changes to the amount of intracellular viral protein, p24, and replicability of HIV-1 were determined on 9 days post-infection by WB and RT assay, respectively." (PMID 31783587, 2019).
neurodegenerative disease (3 papers, 2017 to 2025). A disorder of the central nervous system characterized by gradual and progressive loss of neural tissue and neurologic function. "In summary, UBE3A is positively involved in multiple neurodegenerative diseases where UBE3A normalization protects neuronal death." (PMID 40076922, 2025). "We believe that future studies designing UBE3A-specific PROTAC to target neurodegenerative diseases are worthwhile." (PMID 40076922, 2025). "This review outlines the expression of UBE3A in neurons and glial cells based on published studies, highlights newly identified patterns of UBE3A, such as its secretion, and emphasizes the involvement of UBE3A in neurodegenerative diseases." (PMID 40076922, 2025).
brain disorder (1 paper, 2025). A disease affecting the brain or part of the brain. "Additionally, recent findings highlight the important contributions of glial cells to what were previously considered neuronal defects in neuropsychiatric disorders, prompting us to re-evaluate our understanding of UBE3A-related brain disorders." (PMID 40076922, 2025). "An expanded focus on glial UBE3A—including cell-specific roles and uptake pathways—could uncover novel therapeutic targets for a range of brain disorders." (PMID 40076922, 2025). "Insights gained from studying neuron–glia interactions involving UBE3A may provide new opportunities for therapeutic interventions in various brain disorders." (PMID 40076922, 2025).
UBE3A also shares sentences with these, for which no sentence is quoted: genetic disorder (6 papers); depression (4); cervical tumor (3); lymphoma (3); Pitt-Hopkins syndrome (3); clear cell renal cell carcinoma (2); Epileptic encephalopathy (2); gastric cancer (2); head and neck cancer (2); Huntington disease (2); Insulin resistance (2); Kleefstra syndrome (2); leukemia (2); liver fibrosis (2); oropharyngeal cancer (2); Parkinson (2); prostate (2); prostate intraepithelial neoplasia (2); skin tumors (2); Timothy syndrome (2); Tremor (2); tuberous sclerosis (2); type-2 diabetes (2); advanced sleep phase syndrome (1); AIDS (1); Aphasia (1); argininosuccinic aciduria (1); atrial fibrillation (1); attention deficit-hyperactivity disorder (1); bacterial infection (1).
A further 70 diseases each share a sentence with UBE3A in 1 paper.